AFP (alpha fetoprotein)
Description:
Binds copper, nickel, and fatty acids as well as, and bilirubin less well than, serum albumin. Only a small percentage (less than 2%) of the human AFP shows estrogen-binding properties.
Synonyms: HPAFP; FETA; AFPD
Tractability: Antibody: UniProt places it where antibodies can reach, with medium confidence; UniProt predicts a signal peptide or a membrane-spanning region; its Gene Ontology location is reachable by antibodies, with medium confidence. Other modalities: a drug acting on it is in phase 2 or 3 trials.
Target class: Secreted protein
Gene: Protein-coding gene on chromosome 4 (73,431,138 to 73,456,174, forward strand). Ensembl gene ENSG00000081051.
Subcellular location: Secreted
Subcellular location (Human Protein Atlas): Golgi apparatus; Predicted to be secreted
Pathways (Reactome):
Metabolism of proteins: Post-translational protein phosphorylation; Regulation of Insulin-like Growth Factor (IGF) transport and uptake by Insulin-like Growth Factor Binding Proteins (IGFBPs)
Gene Ontology:
Molecular function: protein binding; small molecule binding
Biological process: response to nutrient levels
Cellular component: endoplasmic reticulum lumen; cytoplasm; extracellular region
Genetic constraint (gnomAD): Loss-of-function variants: 52 observed, 68.03 expected, observed/expected ratio (o/e) 0.76, 90% interval 0.61 to 0.96. The upper end of that interval is the gene's LOEUF score, 0.96, which puts it in group 4 of 6, group 1 being the genes least tolerant of losing a copy. Missense variants: 630 observed, 677.92 expected, observed/expected ratio (o/e) 0.93, 90% interval 0.87 to 0.99. Synonymous variants: 239 observed, 233.61 expected, observed/expected ratio (o/e) 1.02, 90% interval 0.92 to 1.14.
Homologues: Orthologues: macaque AFP (98% identical), chimpanzee AFP (98% identical), dog AFP (82% identical), pig AFP (82% identical), rabbit AFP (76% identical), guinea pig AFP (73% identical), mouse Afp (64% identical), rat Afp (63% identical), tropical clawed frog alb (30% identical). Paralogues in human: ALB (39% identical), AFM (38% identical), GC (16% identical).
Diseases named in the same sentence as AFP in open-access papers:
AFP is named in the same sentence as 624 diseases in open-access papers, as found by Europe PMC text mining. Sharing a sentence is not in itself a finding about the gene and the disease. The quoted sentences say what the papers report.
hepatocellular carcinoma (1,235 papers, 1971 to 2026). A malignant tumor that arises from hepatocytes. "Hepatoid adenocarcinoma of the lung is a rare primary pulmonary malignancy that exhibits morphological traits resembling those seen in hepatocellular carcinoma and is associated with high alpha-fetoprotein expression." (PMID 41704974, 2026). "Alpha-fetoprotein (AFP) is a malignant growth marker for hepatocellular carcinoma and an oncofetal glycoprotein that is encoded by the AFP quality." (PMID 39861718, 2025). "Alpha-fetoprotein (AFP) is a tumor marker commonly associated with malignant liver tumors, particularly hepatocellular carcinoma or benign liver diseases." (PMID 41304988, 2025). "The mechanism underlying Huaier’s ability to reduce AFP levels is likely associated with its inhibitory effect on hepatocellular carcinoma cell proliferation and its promotion of apoptosis, which directly reduces tumor burden and, consequently, AFP production." (PMID 40573279, 2025). "Elevated serum levels of alpha-fetoprotein (AFP) are commonly associated with hepatocellular carcinoma or germ cell tumors." (PMID 40406259, 2025). "Another scRNA-seq study 57 demonstrated that MHC-II expression in alpha-fetoprotein-positive hepatocellular carcinoma is associated with immune dysfunction, including T-cell exhaustion and the accumulation of tumour-promoting macrophages." (PMID 41281745, 2025). "Despite the widespread clinical application of associated biomarkers, such as α-fetoprotein (AFP), for the diagnosis of hepatocellular carcinoma (HCC), their use remains controversial and constrained by limitations." (PMID 40051634, 2025). "Elevated levels of AFP in adults are primarily associated with hepatocellular carcinoma and germ cell tumors, making it a crucial biomarker for the monitoring of these malignancies." (PMID 39771616, 2024). "Alpha-fetoprotein (AFP), a classic hepatocellular carcinoma-specific diagnostic and prognostic marker, still presents limitations." (PMID 38914941, 2024). "Alpha-fetoprotein (AFP) is a diagnostic marker for liver cancer (hepatocellular carcinoma) and germ cell tumors." (PMID 39767566, 2024). "There is further analysis of the diagnostic role of ApoB/ApoA1 ratio in differentiating HCC from LC or CHB and in combination with AFP, a common diagnostic marker for hepatocellular carcinoma." (PMID 38744926, 2024). "Levels of C-reactive protein (CRP) and alpha-fetoprotein (AFP) in immunotherapy (CRAFITY) scores are associated with the prognosis of patients with hepatocellular carcinoma (HCC)." (PMID 39555053, 2024). "As a crucial biomarker for the early warning and prognosis of liver cancer diseases, elevated levels of alpha-fetoprotein (AFP) are associated with hepatocellular carcinoma and germ cell tumors." (PMID 39771616, 2024). "Alpha-fetoprotein (AFP) serves as a crucial diagnostic marker for primary hepatocellular carcinoma (HCC) and germ cell tumors (GCTs), with rare instances of significantly elevated levels in other diseases." (PMID 38812781, 2024). "Normal human serum AFP concentrations are less than 10 ng/mL, and high AFP levels in adult serum have been associated with the development of liver cell carcinoma." (PMID 38998732, 2024). "An additional point of note is the correlation of ctDNA VAF with tumor size and AFP levels in hepatocellular carcinoma, as well as an association between ctDNA positivity and macrovascular invasion found by Ge Z and colleagues." (PMID 38201440, 2023). "AFP can be used clinically as a diagnostic marker for hepatocellular carcinoma and a target for hepatocellular carcinoma immunotherapy and has multiple biological functions." (PMID 37919386, 2023).
hepatocellular carcinoma (continued). "In patients with hepatocellular carcinoma, the level of miRNA-223-3p in circulation is significantly reduced, and the diagnostic accuracy of alpha-fetoprotein can reach 100% for intermediate and advanced hepatocellular carcinoma." (PMID 37546394, 2023). "In clinical practice, serum AFP is widely acknowledged as a surveillance and diagnostic biomarker for hepatocellular carcinoma (HCC)." (PMID 37781207, 2023). "AFP is one of the major tumor-associated proteins produced by the liver, and its production is increased in response to carcinogenesis, especially hepatocellular carcinoma." (PMID 37755751, 2023). "The hepatocellular cancer patients showed a higher sensitivity to hPG80 than alpha-fetoprotein (AFP) – the standard available diagnostic marker for hepatocellular cancer." (PMID 37016331, 2023). "Comparably, we reported a good diagnostic performance for microRNA-23a that surpasses AFP in HCV-related hepatocellular carcinoma patients." (PMID 37587273, 2023). "Wong LL reported that elevated alpha-fetoprotein levels, low levels of albumin and tumours > 5 cm in size were associated with increased 1-year mortality after hepatic resection for early-stage hepatocellular cancer in a retrospective study." (PMID 36494837, 2022). "Serum angiogenetic markere neuropilin-1 (NRP-1) combinated with AFP can enhance the diagnostic power in hepatocellular carcinoma, and predicted the poor prognosis." (PMID 34991620, 2022). "Alpha fetoprotein (AFP) is associated with hepatocellular carcinoma (HCC) by stimulating the proliferation, metastasis and drug resistance." (PMID 36181321, 2022). "AFP is a biomarker for hepatocellular carcinoma (HCC), the fourth leading cause of global cancer deaths with a mortality rate of almost 100%14." (PMID 35840635, 2022). "Although alpha fetoprotein (AFP) has low specificity as a serologic diagnostic marker for hepatocellular carcinoma, its sensitivity remains relatively high (around 60%)." (PMID 35677563, 2022). "AFP is a significant biomarker that helps in the detection of liver carcinoma, although diagnostic approaches based on AFP are still far from satisfactory due to its poor sensitivity and specificity." (PMID 35068348, 2022). "In a clinical study of patients with hepatocellular carcinoma, plasma HSP90α has been found to be of diagnostic value for early hepatocellular carcinoma, and the combination of AFP can improve the diagnostic efficiency." (PMID 36158677, 2022). "Though serum tumor markers, such as AFP and tumor-associated antigens (TAAs), are engaging alternatives for monitoring and early diagnosis of hepatocellular carcinoma, their sensitivities and specificities remain disappointing." (PMID 35251971, 2022). "CASP3 is a downstream effector of cytosine protease in apoptosis, and it is frequently overexpressed in hepatocellular carcinoma associated with high serum levels of AFP." (PMID 35154607, 2021). "Alpha fetoprotein (AFP) is an oncofetal protein that is highly expressed in fetal cells and in most patients with hepatocellular carcinoma (HCC), and it is a diagnostic marker of liver cancer." (PMID 33898423, 2021). "Dendritic cells (DC) as professional antigen presenting cells are able to prime T-cells against the tumor-associated antigen α-fetoprotein (AFP) for immunotherapy of hepatocellular carcinoma (HCC)." (PMID 34282787, 2021). "In hepatocellular carcinoma, the exo_circ_0006602 was a more efficient diagnostic biomarker than the classic tumour serum markers: alpha-fetoprotein (AFP) (AUC = 0.694, p < 0.002) and CEA (AUC = 0.589, p = 0.146)." (PMID 34944400, 2021).
hepatocellular carcinoma (continued). "The abnormal high expression of AFP is intimately associated with hepatoma progress, but the mechanism of transcriptional regulation and singularly activation of AFP gene in hepatoma cells is not clear." (PMID 33794968, 2021). "At present, the diagnostic accuracy of alpha-fetoprotein (AFP) for hepatocellular carcinoma (HCC) surveillance is insufficient." (PMID 33628341, 2021). "The abnormal high expression of alpha-fetoprotein (AFP) is intimately associated with hepatoma progress, but the mechanism of transcriptional regulation and singularly activation of AFP gene in hepatoma is not clear." (PMID 33794968, 2021). "AFP levels serve as diagnostic marker of liver injury such as hepatocellular carcinoma or Hepatitis C infection." (PMID 32784936, 2020). "The diagnostic accuracy of LIMK1 in the diagnosis of hepatocellular carcinoma was higher than that of AFP." (PMID 32168432, 2020). "Total tumor volume (TTV) and serum alfa fetoprotein (AFP) level are important risk factors linked with the high possibility of hepatocellular carcinoma (HCC) recurrence." (PMID 32426129, 2020). "The discovery a few years later of AFP in animal models with hepatocellular carcinoma (HCC) led to clinical investigations that associated AFP with HCC." (PMID 32012846, 2020). "In multivariable model, four more variables are screened out as independent risk factors for 5-year OS and RFS: Child-Pugh, AFP level, diameter of hepatocellular carcinoma and PVTT type." (PMID 32928121, 2020). "An elevated serum AFP level is usually associated with hepatocellular carcinoma, yolk sac tumor, cirrhosis, and hepatitis." (PMID 32093729, 2020). "In hepatocellular carcinoma, miR-1236-3p down-regulates alpha-fetoprotein (AFP), thus causing PTEN accumulation, which inhibits the PI3K/Akt pathway." (PMID 29743816, 2018). "In patients with known risk factors for hepatocellular carcinoma and an elevated AFP, the diagnosis should remain on the differential even in the absence of hepatic lesions." (PMID 29881547, 2018). "Regulation of cell-type specific effectors downstream of TYRO3 has also been reported in specific tumor types, including Microphthalmia-associated transcription factor (MITF) in melanoma 48] and alpha-fetoprotein (AFP) in hepatocellular carcinoma." (PMID 30501104, 2018). "Here, we report the case of a patient who was diagnosed with hepatic IPT associated with PBC and elevated alpha-fetoprotein (AFP) lectin 3 (L3) fraction mimicking hepatocellular carcinoma (HCC)." (PMID 30203247, 2018). "In this study the AFP was also confirmed as an independent risk factor for the development of hepatocellular carcinoma." (PMID 28638828, 2017). "Clinical studies have shown that the level of serum AFP is associated with a series of malignant characteristics of hepatocellular carcinoma." (PMID 27835879, 2016). "New markers such as hepatoma specific gamma-glutamyl transferase (HS-GGT) and hepatoma-specific AFP (HS-AFP) have been developed to improve the diagnostic sensitivity and specificity for HCC patients." (PMID 27286460, 2016). "Clarification of these mechanisms will provide further insights into the regulation of AFP in hepatoma cells, and offer a new therapy for liver cancer caused by HBV." (PMID 27835879, 2016). "The AFP level measurement has been used as a diagnostic marker of primary hepatocellular carcinoma since 1970s." (PMID 25922775, 2015). "The reappearance of AFP in the circulation of adults is associated with liver regeneration, hepatitis, chronic liver diseases and malignant growth, including hepatomas and teratomas." (PMID 26199728, 2015). "Hepatocellular Carcinoma is the third most common cause of cancer related death worldwide, often diagnosed by measuring serum AFP; a poor performance stand-alone biomarker." (PMID 23935864, 2013). "α-Fetoprotein (AFP) is a tumour-associated antigen in hepatocellular carcinoma (HCC) and is a target for immunotherapy." (PMID 20087354, 2010).
hepatocellular carcinoma (continued). "An AFP value above 400 – 500μg/L has been considered to be diagnostic for hepatocellular carcinoma (HCC) in patients with cirrhosis." (PMID 21532726, 2009). "AFP level is, however, elevated in patients with hepatocellular carcinoma and in those with other liver diseases associated with liver regeneration." (PMID 19674468, 2009). "Alpha fetoprotein levels ≥200 and 400 ng/mL in patients with an identifiable liver mass by imaging techniques are diagnostic of hepatocellular carcinoma with high specificity." (PMID 17288606, 2007). "High Alpha fetoprotein serum levels have been found in 60–70% of patients with Hepatocellular carcinoma; nevertheless, there are other causes that increase this protein." (PMID 17288606, 2007). "Antibody to hepatitis C virus (anti-HCV) was found to be an independent risk factor for hepatocellular carcinoma and raised serum alpha-fetoprotein (AFP) level." (PMID 7515263, 1994). "However, the elevation of Alpha-fetoprotein (AFP) in gastric cancer, a marker more commonly associated with hepatocellular carcinoma or germ cell tumors, is exceedingly rare and suggests an unusual biological behavior or specific histological subtypes." (PMID 41800062, 2026). "AFP serves as a key diagnostic marker for hepatocellular carcinoma." (PMID 41008874, 2025). "The inverse relationship between AFP and malignancy risk may reflect its role in distinguishing benign conditions (e.g., hepatocellular carcinoma, where AFP rises)." (PMID 41300279, 2025). "Children with BSEP deficiency are at high risk of developing hepatobiliary malignancies like hepatocellular carcinoma or cholangiocarcinoma; thus, regular monitoring every 6 months of alpha-fetoprotein and annual abdominal sonography are required for these patients." (PMID 40729246, 2025). "AFP is specifically associated with hepatocellular carcinoma and may be elevated in other hepatic diseases as well." (PMID 39888414, 2025). "Although the serum alpha-fetoprotein (AFP) test is routinely used for risk stratification of hepatocellular carcinoma, its sensitivity and specificity are significantly limited, making it difficult to provide accurate diagnosis and support treatment using this test." (PMID 40649911, 2025). "The foetal state of some hepatocellular carcinoma may be of prognostic significance, as AFP serum levels have previously been associated with poor outcomes in hepatocellular carcinoma." (PMID 38195504, 2024). "Current studies aim at comparative and summative evaluation of different methods, with Japan and other countries implementing simultaneous determination of PIVKA II and AFP as a screening method to monitor patients at high risk of developing hepatocellular carcinoma." (PMID 36899960, 2023). "When confounding variables were adjusted, multivariate cox regression analysis demonstrated the following 4 variables were independently association with the prognosis of hepatocellular carcinoma patients after partial hepatectomy: Differentiation, Tumor size, AFP, and Fibrosis." (PMID 36717904, 2023). "Two patients were diagnosed with high serum AFP levels (>20 ng/mL); other conditions that may cause an increase in AFP, such as hepatocellular carcinoma, hepatitis, and pregnancy, were excluded." (PMID 37017469, 2023). "Other TAAs and TSAs, such as alpha-fetoprotein (AFP), which is over-expressed in the majority of hepatocellular carcinoma, and prostate stem cell antigen (PSCA), which is associated with the development of prostate cancer, also showed great synergistic effect with HSP70 in multiple cancers." (PMID 37189349, 2023). "The sensitivity, specificity, and diagnostic odds ratio of AFP and AFP-L3 for hepatocellular carcinoma were analyzed and compared, which found that AFP-L3 had high-specificity and low-sensitivity in diagnosing early hepatocellular carcinoma." (PMID 36072925, 2022).